MRM2 (mitochondrial rRNA methyltransferase 2)
Description:
S-adenosyl-L-methionine-dependent 2'-O-ribose methyltransferase that catalyzes the formation of 2'-O-methyluridine at position 1369 (Um1369) in the 16S mitochondrial large subunit ribosomal RNA (mtLSU rRNA), a universally conserved modification in the peptidyl transferase domain of the mtLSU rRNA. This activity may require prior 2'-O-methylguanosine modification at position 1370 (Gm1370) by MRM3. Essential for late-stage assembly of mtLSU required for efficient translation of mitochondrial DNA encoded proteins; methyltransferase activity is not required for this function. Essential for mitochondrial respiratory function.
Synonyms: FJH1; FTSJ2; RRMJ2; HEL97; MTDPS17
Tractability: Small molecule: a structure with a bound ligand is known; it has a binding pocket of medium quality. PROTAC: ubiquitination databases record sites on it.
Gene: Protein-coding gene on chromosome 7 (2,234,195 to 2,242,205, reverse strand). Ensembl gene ENSG00000122687.
Subcellular location: Mitochondrion
Pathways (Reactome):
Metabolism of RNA: rRNA modification in the mitochondrion
Gene Ontology:
Molecular function: rRNA (uridine-2'-O-)-methyltransferase activity; methyltransferase activity
Biological process: mitochondrial large ribosomal subunit assembly; rRNA processing; ribosomal large subunit assembly; rRNA 2'-O-methylation; rRNA methylation
Cellular component: mitochondrial matrix; mitochondrion; nucleolus
Genetic constraint (gnomAD): Loss-of-function variants: 16 observed, 13.82 expected, observed/expected ratio (o/e) 1.16, 90% interval 0.78 to 1.72. The upper end of that interval is the gene's LOEUF score, 1.72, which puts it in group 6 of 6, group 1 being the genes least tolerant of losing a copy. Missense variants: 325 observed, 330.73 expected, observed/expected ratio (o/e) 0.98, 90% interval 0.9 to 1.08. Synonymous variants: 138 observed, 134.27 expected, observed/expected ratio (o/e) 1.03, 90% interval 0.89 to 1.18.
Homologues: Orthologues: chimpanzee MRM2 (98% identical), macaque MRM2 (95% identical), mouse Mrm2 (79% identical), dog MRM2 (78% identical), rat Mrm2 (78% identical), guinea pig MRM2 (77% identical), pig MRM2 (74% identical), tropical clawed frog mrm2 (52% identical), zebrafish mrm2 (50% identical), Drosophila melanogaster Mrm2 (39% identical), Caenorhabditis elegans F45G2.9 (37% identical). Paralogues in human: FTSJ3 (28% identical), FTSJ1 (28% identical).
Diseases named in the same sentence as MRM2 in open-access papers:
MRM2 is named in the same sentence as 21 diseases in open-access papers, as found by Europe PMC text mining. Sharing a sentence is not in itself a finding about the gene and the disease. The quoted sentences say what the papers report.
MELAS (5 papers, 2017 to 2022). "A patient manifesting symptoms of mitochondrial encephalopathy, lactic acidosis, and stroke-like episodes (MELAS) syndrome was found to carry a mutation in MRM2." (PMID 32765591, 2020). "MRM2—The homozygous missense variant Chr7: 2274933 C > T (p.Gly189Arg) in MRM2 was identified in a pediatric patient with MELAS." (PMID 33917098, 2021). "We describe homozygous mutations in MRM2 gene encoding the mitochondrial 16S rRNA methyltransferase MRM2 in a patient with MELAS-like encephalomyopathy, multiple OXPHOS deficiency and reduction of mtDNA copy number." (PMID 28973171, 2017). "Although a confirmation of the clinical phenotype in a second independent patient is still lacking, it is possible that mutations in MRM2 cause a MELAS-like phenotype, and suggests the genetic screening of MRM2 in patients with a m.3243 A > G negative MELAS-like disease." (PMID 29980628, 2018). "Our findings establish that defective MRM2 causes a MELAS-like phenotype, and suggests the genetic screening of the MRM2 gene in patients with a m.3243 A > G negative MELAS-like presentation." (PMID 28973171, 2017).
glioma (3 papers, 2021 to 2025). A benign or malignant brain and spinal cord tumor that arises from glial cells (astrocytes, oligodendrocytes, ependymal cells). "Our findings revealed that MRM2, NSUN4, TFB1M, and TRMT2B were correlated significantly with most immunomodulators in glioma, whereas MRM1 and RPUSD4 were correlated negatively." (PMID 34566979, 2021). "Results revealed that MRM2 and TRMT2B were differentially expressed between NBTs, low-grade glioma tissues, and high-grade glioma tissues." (PMID 34566979, 2021).
non-small cell lung carcinoma (3 papers, 2014 to 2021). A group of at least three distinct histological types of lung cancer, including non-small cell squamous cell carcinoma, adenocarcinoma, and large cell carcinoma. "Furthermore, gene expression analysis identified MRM2 (referred to as FTSJ2) as a new oncogene that is amplified in non-small cell lung cancer." (PMID 33917098, 2021). "miRNA-542-3p is down-regulated in non-small cell lung cancer cells, and it was reported that it may exert tumor-suppressive functions by targeting and upregulating MRM2." (PMID 33917098, 2021). "MiR-542-3p functions as a tumor suppressor by targeting mitochondrial rRNA methyltransferase 2 (MRM2; also known as FTSJ2) in the progression of non-small cell lung cancer." (PMID 34853725, 2021).
epilepsia partialis continua (1 paper, 2017). "In conclusion, MRM2 is a new disease-causing gene in mtDNA metabolism pathway that should be considered in the differential diagnosis of childhood-onset epilepsia partialis continua and stroke-like episodes." (PMID 28973171, 2017).
cancer (4 papers, 2014 to 2021). A tumor composed of atypical neoplastic, often pleomorphic cells that invade other tissues. "However, only five similar proteins were identified in all three cancer cell lines and these include SSSCA1 as expected, Tankyrase 1 (TNKS1), γ-tubulin (TUBG1), and the poorly characterized rRNA methyltransferase MRM2 and membrane associated VAPA." (PMID 32170109, 2020).
mitochondrial disease (2 papers, 2021 to 2022). "Finally, using a Drosophila melanogaster model, we show that MRM2 is essential for the development and homeostasis of neuronal and muscular tissues, often affected in mitochondrial diseases." (PMID 35177605, 2022).
MRM2 also shares sentences with these, for which no sentence is quoted: tumor (5 papers); lung carcinoma (2); MELAS syndrome (2); breast carcinoma (1); depression (1); encephalomyopathy (1); Failure to thrive (1); lactic acidosis (1); lung adenocarcinoma (1); mitochondrial cytopathy (1); mitochondrial DNA depletion syndrome (1); mitochondrial encephalomyopathy (1); rhabdomyosarcoma (1); schizophrenia (1); Stroke (1).